IGF1 (insulin like growth factor 1)
Diseases named in the same sentence as IGF1 in open-access papers (continued):
Sharing a sentence is not in itself a finding about the gene and the disease.
depression (continued). "In this context, IGF-1 has been assessed for its correlation with subjective scales of depression." (PMID 37894932, 2023). "A potential link between decreases in IGF-1 expression and depression in rat models and peripheral IGF-1 levels could potentially be a marker of depression in human subjects with MDD and bipolar disorder." (PMID 37242525, 2023). "Both cortisol and IGF-1 levels were positively correlated with the Hamilton Rating Scale for Depression score in patients with MDD, whereas cortisol level was positively correlated and IGF-1 level was negatively correlated with the Brief Psychiatric Rating Scale score in patients with schizophrenia." (PMID 36670169, 2023). "Moreover, the results demonstrated that intra-mPFC infusion of IGF-1 nAb 2 h after ketamine injection blocked the antidepressant-like actions of this drug in the murine LPS-induced depression model." (PMID 35577782, 2022). "Moreover, intra-mPFC infusion of IGF-1 nAb 2 h post-ketamine blocked the antidepressant-like effects of ketamine in a murine lipopolysaccharide (LPS)-induced depression model." (PMID 35577782, 2022). "Further studies are needed to examine whether ketamine can induce persistent IGF-1 release in the mPFC of rodent depression models such as the LPS-challenged animals in which IGF-1 levels in the frontal cortex are decreased." (PMID 35577782, 2022). "Similarly, IGF1/IGF1R signaling declined during pregnancy, which is notable given that IGF1 deficiency in the hippocampus is linked to depression Wnt5a signaling in endothelial cells also declined during pregnancy compared with virgin." (PMID 36239981, 2022). "In all of them, a decrease in IGF-1 was observed during the use of antidepressants, but the data are insufficient to conclude that IGF-1 may be a predictor of response to treatment in depression." (PMID 34362162, 2021). "The activity of IGF-1 may be modulated by the immune system, whose confirmed role in the pathogenesis of depression is widely reported in scientific publications." (PMID 34362162, 2021). "The activity of IGF-1 being modulated by the immune system is a very common hypothesis in the pathogenesis of depression." (PMID 34362162, 2021). "In patients with liver cancer complicated by depression, IGF1/VEGFA/SERPINE1 may play an important role in the pathogenesis and development of the disease, but the specific mechanism has not been clarified." (PMID 33960267, 2021). "However, recently Troyan and Levada showed that patients diagnosed with depressive disorders had higher levels of IGF-1, but lower levels of brain-derived neurotrophic factor (BDNF)." (PMID 34574400, 2021). "Impairments in the brain IGF-1 concentrations might be responsible for some aspects of major depressive disorder (MDD) pathogenesis, whereas peripheral IGF-1 could have the marker value." (PMID 32384884, 2020). "The authors suggested that discrepancies between total and biologically active free IGF-1 levels could be due to adaptation mechanisms to changes typically found in major depression." (PMID 32922315, 2020). "Parkinson disease patients score lower on Hospital-associated Anxiety and Depression Scale after supplementing blackcurrant anthocyanins (BCA), which may be associated with IGF-1 function." (PMID 29865234, 2018). "In humans circulating levels of IGF-1 peptide correlate negatively with symptoms of low mood, depression and anxiety so expression levels of IGF-1 may be a useful indicator of positive affect." (PMID 28238777, 2017). "Besides the behavioral alterations, this report for the first time characterized the impact of chronic antidepressant treatment on the IGF-1 system responsible for the biological function of IGF-1 in the OBs of an animal model of depression." (PMID 26610812, 2016). "IGF-1 has also been suggested to be a as possible target for therapy in depression." (PMID 25880744, 2015). "Several components of the GH/IGF-1 axis also modulate anxiety and depression." (PMID 25386163, 2014).
depression (continued). "Reduced IGF-1 levels could be a potential biomarker of depression in animal models." (PMID 41340853, 2025). "Nonetheless, IGF-1 alterations could be a side effect from prior imbalance in depression." (PMID 40141202, 2025). "In addition, depression induced by IL-6 can result in a reduction in food intake, an increase in resting energy expenditure, and a suppression of anabolic hormones such as growth hormone and insulin-like growth factor (IGF)-1." (PMID 37763079, 2023). "Therefore, in a group of mice already submitted to a behavioral test of depression, we examined the expression of some neurotrophic/growth factors associated with the pathogenesis of depressive disorders, such as BDNF, IGF-1, nerve growth factor (NGF), and fibroblast growth factor 2 (FGF-2)." (PMID 37298063, 2023). "Insulin-like growth factor 1 (IGF-1) is a polypeptide hormone that plays a pivotal role in the development of the brain, and recent evidence suggests that it may play a role in the pathogenesis of depression." (PMID 37242525, 2023). "In addition to BDNF, also IGF-1, FGF-2, and NGF have been implicated in depressive disorders." (PMID 35886944, 2022). "Serum IGF-1 level in PSD patients at different degrees of depression is different and the difference is statistically significant, which might be related to the fact that serum IGF-1 level could lead to PSD due to its impact on hypothalamus-pituitary-adrenal axis." (PMID 30181997, 2018). "IGF-1 is cytoprotectant and changes in this peptide signaling may be involved in the pathogenesis of neurological and psychiatric disorders, including anxiety and depression." (PMID 29108028, 2017). "Moreover, peripheral IGF-1 levels may play a predictive role in the occurrence of depression, thus low IGF-1 levels in women and high in men predict the development of MDD in general population." (PMID 29093741, 2017). "Given the levels of IGF-1 have been found to be low in rodent models of depression, the absence of this anti-inflammatory factor may exacerbate the neuroinflammatory and anti-neuroplastic state in depression." (PMID 23382717, 2013). "Significant negative correlations were found between IGF-1 levels and RPQ-13, GAD-7, and PHQ-9 scores across all TBI severity groups, with lower IGF-1 Z-scores correlating with higher symptoms of TBI, depression, and anxiety." (PMID 40697802, 2025). "As IGF-1 Z-scores decreased below 0, there were significant increases in RPQ-13, GAD-7, and PHQ-9 scores, indicating a rise in TBI symptoms, depression, and anxiety, with most severe symptoms observed at Z-scores of negative 2 or below." (PMID 40697802, 2025). "Therefore, the aim of our study was to examine whether the intracerebroventricular administration of IGF-1 reduces anxiety and depressive disorders and influences peripheral inflammation in a rat model of sporadic Alzheimer’s disease, and whether this effect is dependent on the stage of the disease." (PMID 40801621, 2025). "The abnormalities of IGF-1 in MDD patients have been suggested as a marker and predictive role of the neurotrophin for depression and treatment effectiveness." (PMID 38362105, 2024). "As an important factor both on glutamate release and on IGF-1 localization in CNS, SNAP23 is evidenced to be closely related to depression." (PMID 38674428, 2024). "There was a significant difference in IGF-1 levels between the two groups, and serum IGF-1 levels were significantly increased in patients with first-episode and drug-naïve depression (MDD:149.81 ± 34.35 ng/ml, control:128.23 ± 25.83 ng/ml, p<0.05)." (PMID 38919642, 2024). "The primary outcome was the patient’s severity of depression symptomatology using the CES-D score; GH, IGF-1 levels, and tumor characteristics were also measured." (PMID 34248479, 2021). "Thus, disturbances in the IGF-1 system could be responsible for the course of depression." (PMID 26610812, 2016).
depression (continued). "Higher IGF-1 levels have been found in depressive patients with alcohol use disorder (AUD), whereas others detected no statistical effect of depression comorbidity in the plasma levels of IGF-1 in AUD patients during abstinence." (PMID 40141202, 2025). "This study was the first to comprehensively examine the impacts of forest bathing on female participants with depression and depressive tendencies, using indicators such as SDS, POMS, serotonin, oxytocin, IGF-1, subjective sleep quality, and subjective fatigue symptoms." (PMID 40277811, 2025). "Therefore, the current investigation was conducted to explore the correlations between depression, anxiety, and CFS due to long COVID and CRP and PGE2, GAL-GALR1 signaling, insulin resistance, PAI1 and IGF1, and neuronal damage markers." (PMID 40048451, 2025). "For patients with mTBI and pre-morbid depression, a strong, negative correlation between IGF-1 Z-scores and PHQ-9 scores that reached statistical significance was seen (τ = −0.51, p = 0.0004)." (PMID 40697802, 2025). "IGF-1 can activate the CREB/PGC-1α signaling pathway to regulate the expression of genes such as NRF1, TFAM, and the mitochondrial dynamics-related protein Drp1, promoting mitochondrial biogenesis and improving function, ultimately alleviating depression." (PMID 40699781, 2025). "Although multiple studies have investigated IGF-1 in depression-related disorders, few studies have focused on patients with a first episode of clearly diagnosed depression who had never used antidepressants before." (PMID 38919642, 2024). "Elevated serum IGF-1 levels in PD patients have been negatively correlated with nonmotor symptoms, such as anxiety, depression, and cognitive dysfunction, and combining IGF-1 with EGF enhances the diagnostic value for PD." (PMID 38699559, 2024). "Meta-analyses demonstrated that IGF-1 levels in patients with depression were increased in serum samples but not plasma samples." (PMID 38919642, 2024). "Therefore, IGF-1 and VEGF also have critical roles during the process of exercise improving depression." (PMID 37239191, 2023). "This study shows that serum IGF-1 levels were correlated with the nonmotor symptoms of anxiety, depression, and cognitive dysfunction and that EGF levels were correlated with cognitive dysfunction." (PMID 36383265, 2023). "Overall, exercise can promote the expression of BDNF and CREB by increasing SIRT1 expression in the hippocampus, and moreover, it can activate the SIRT1/IGF-1/GAP-43 and SYN signaling pathways to increase the volume of SVZ and SGZ, improving neurogenesis, and eventually relieving depression." (PMID 37239191, 2023). "In some studies, IGF-1 peripheral levels were found to be significantly increased in depression regardless of ethnicity, since some works were done in Europe, North America and Japan." (PMID 37894932, 2023). "In contrast, peripheral IGF-1 has received far more attention in the last few decades, not just in depression, but also in other mental conditions such as schizophrenia and bipolar disorder." (PMID 37894932, 2023). "This aspect may be important in establishing peripheral IGF-1 or IGF-2 levels as objective distinguishing biomarkers that can reflect changes in subjective scales of clinical use, such as the Hamilton Depression Rating Scale (HDRS) in the case of depression." (PMID 37894932, 2023). "The results of this study suggest a potential relationship between lower levels of serum IGF-1 and masticatory dysfunction in community-dwelling older people, regardless of age, depression, or body composition." (PMID 36078393, 2022). "The present study aimed to investigate whether the BDNF, VEGF, S100B, and IGF-1 in serum levels can be helpful to identify MDD in knee OA patients and to evaluate the potential relationship of these neurotrophins with depression and pain assessments." (PMID 36386998, 2022).
depression (continued). "Therefore, the present study was designed to explore the mRNA expression and protein concentrations of IGF-1, as well as of IGF-1-binding protein levels (IGFBP-2, IGFBP-4, IGFBP-3, and IGFBP-6), in an animal model of depression." (PMID 26610812, 2016). "Finally, we investigated the release of neurotrophic factors, including IGF-1 and BDNF (brain derived neurotrophic factor), in microglial cells in cultures in an animal model of depression." (PMID 25814933, 2015). "Additionally, studies showed that the plasma level of another neurotrophic factor, insulin-like growth factor 1 (IGF-1), was significantly higher in MDD patients compared to healthy controls and may be related to the pathology of depression." (PMID 40365616, 2025). "Furthermore, no biomarker changes, except for IGF-1 and depression scores in the MBSR+CCT group, were significantly correlated with or mediated the gains observed in cognitive, emotional, mindfulness, or fitness outcomes." (PMID 40283415, 2025). "Results of the case-control study demonstrated that serum IGF-1 levels are significantly increased in patients with first-episode and drug-naïve depression compared with healthy controls independent of gender, age and severity of depression." (PMID 38919642, 2024). "This may suggest that the levels of IGF-1 might be increased in depression regardless of treatment conditions." (PMID 37894932, 2023). "Nonetheless, according to the neurotrophic hypothesis, depression could be the result of the stress-induced reduced expression of neurotrophic factors such as Brain-Derived Neurotrophic Factor (BDNF), IGF-1 or Glial cell line-derived neurotrophic factor (GDNF)." (PMID 37894932, 2023). "Molecular and behavioral studies deepened the role of neurotrophic/growth factors (such as BDNF, NGF, IGF-1, and FGF-2) in depression, demonstrating that the levels of those factors were reduced in animal models and in depressed and/or stressed patients (“neurotrophic hypothesis of depression”)." (PMID 35886944, 2022). "However, this history should be taken with caution because the role of IGF-1 is not conclusive for the treatment and diagnosis of depression." (PMID 34574400, 2021). "IGF-1 did not play an important role in the development of depression over time." (PMID 27544533, 2016). "However, IGF-1 was significantly and negatively correlated with age and positively with the number, duration, and severity of depressive episodes, according to the Clinical Global Impression Severity (CGIS) and the Montgomery–Asberg Depression Rating Scale (MADRS)." (PMID 40141202, 2025). "To further confirm the role of IGF-1 in the mPFC in the antidepressant-like actions of ketamine, we examined whether intra-mPFC infusion of IGF-1 nAb 2 h after ketamine injection can reverse depression-like behaviors induced by LPS challenge in the TST and FST." (PMID 35577782, 2022). "In our case, we did not measure IGF-1, but we did measure IGF-2, since peripheral IGF-2 has never been measured in the context of human depression." (PMID 37894932, 2023). "In paired analyses, GH levels, but not IGF-1 levels, were closely and significantly correlated with CES-D scores, and surgery had a profound effect on the decline in both absolute scores and the proportion of individuals classified as having clinical depression." (PMID 34248479, 2021).
Hypoglycemia (136 papers, 2000 to 2026). A decreased concentration of glucose in the blood. "When it is associated with hypoglycemia and high levels of IGF-1, it is possible to diagnose Doege–Potter syndrome, excluding alternative causes." (PMID 40559210, 2025). "Numerous investigations have demonstrated that puerarin can cause hypoglycemia via increasing the expression of PPARα, insulin-like growth factor-1 (IGF-1), and insulin receptor substrate-1 (IRS-1)." (PMID 38666911, 2024). "Assuming that hGH has a less relevant influence on the glucose metabolism pathway than IGF-1, these results support the utilization of hGH in clinical trials in place of IGF-1 to reduce the risk of hypoglycemia." (PMID 36833418, 2023). "In infants with history of hypoglycaemia, hyperbilirubinemia, poor growth, midline defects, microphallus, low IGF-1 and IGFBP-3, MPHD, such as TSH and ACTH deficiency, and/or an abnormal brain MRI, the diagnosis of GHD is possible without stimulation test." (PMID 35250894, 2022). "With regards to clinical applicability, systemic IGF-1 delivery is severely limited by the risk of side effects, including hypoglycemia, lymphoid hyperplasia, body fat accumulation, electrolyte imbalances, and mental status changes." (PMID 34249891, 2021). "While studies have shown improved physical performance, side effects such as hypoglycemia and risk for the development of cancer have limited the use of IGF-1 for this indication." (PMID 30591079, 2018). "In conclusion, post- and particularly pre-operative IGF-1 serum concentrations help in identifying patients at risk for developing post-load hypoglycemia." (PMID 24736741, 2014). "The main finding of our study was that post-load hypoglycemia approximately one year after bariatric surgery was closely associated with increased circulating IGF-1 concentrations before and after surgery." (PMID 24736741, 2014). "Post-operative IGF-1 serum concentration was also predictive for the risk of hypoglycemia, alone and even after adjustment for other potential risk factors such as age, WHR and triglycerides." (PMID 24736741, 2014). "Here we identified increased IGF-1 concentrations before and after surgery as a major risk factor for post-load hypoglycemia." (PMID 24736741, 2014). "We detected a clinically applicable “threshold” of 111 ng/ml in pre-operative IGF-1 concentration which can be somewhat useful in assessing the risk of hypoglycemia." (PMID 24736741, 2014). "Insulin-like growth factor 1 (IGF-1) receptor α is overexpressed in pancreatic islets in nesidioblastosis and administration of recombinant IGF-1 causes hypoglycemia." (PMID 24736741, 2014). "In conclusion, NICTH should be considered in patients who present with recurrent hypoglycemia associated with suppressed serum insulin and IGF1 levels." (PMID 24616774, 2013). "This contrasts the recent report of an association between low IGF1 and recurrent severe hypoglycemia during pregnancy in women with type 1 diabetes." (PMID 23781301, 2012). "We found a severe GH deficiency, defined by a peak response to insulin-induced hypoglycemia less than 3 ng/dL and IGF1 concentrations less than -2SDS." (PMID 19128470, 2009). "However, the increased umbilical CSH as a result of fetal hypoglycemia was associated with the maintenance of fetal concentrations of IGF1." (PMID 37374044, 2023). "However, there is still a need to identify other hormonal and physiological insulin/IGF-1 independent activators of Akt to avoid associated side effects such as hypoglycemia when used therapeutically." (PMID 36169399, 2022). "The most common adverse effect of mecasermin is mild hypoglycemia caused by IGF1." (PMID 32066763, 2020). "The ROC analysis of the risk estimation by pre-operative IGF-1 revealed an AUC of 0.79 (95%CI: 0.64–0.94, p = 0.0033) and hence showed a good accuracy to detect hypoglycemia one year after bariatric surgery (ROC-AUC of 1.00 represents a perfect test and 0.50 an insignificant test)." (PMID 24736741, 2014).